NTSR2 (neurotensin receptor 2)
Description:
Receptor for the tridecapeptide neurotensin. It is associated with G proteins that activate a phosphatidylinositol-calcium second messenger system.
Synonyms: NTR2
Tractability: Small molecule: a high-quality ligand is known; it belongs to a druggable protein family. Antibody: its Gene Ontology location is reachable by antibodies, with high confidence; UniProt places it where antibodies can reach, with medium confidence; UniProt predicts a signal peptide or a membrane-spanning region. PROTAC: a small molecule that binds it is known.
Target class: Family A G protein-coupled receptor; Peptide receptor (family A GPCR); Membrane receptor; Short peptide receptor (family A GPCR); Neurotensin receptor
Chemical probes: CHEMBL1766944
Gene: Protein-coding gene on chromosome 2 (11,658,178 to 11,670,195, reverse strand). Ensembl gene ENSG00000169006.
Subcellular location: Cell membrane
Pathways (Reactome):
Signal Transduction: G alpha (q) signalling events; Peptide ligand-binding receptors
Gene Ontology:
Molecular function: G protein-coupled neurotensin receptor activity; G protein-coupled receptor activity
Biological process: cell surface receptor signaling pathway; neuropeptide signaling pathway; sensory perception; G protein-coupled receptor signaling pathway
Cellular component: plasma membrane; membrane
Genetic constraint (gnomAD): Loss-of-function variants: 22 observed, 17.87 expected, observed/expected ratio (o/e) 1.23, 90% interval 0.88 to 1.73. The synonymous counts are far from expectation, so gnomAD's model fits this gene poorly and the ratio says little. Missense variants: 570 observed, 484.39 expected, observed/expected ratio (o/e) 1.18, 90% interval 1.1 to 1.26. Synonymous variants: 291 observed, 218.78 expected, observed/expected ratio (o/e) 1.33, 90% interval 1.21 to 1.47.
Homologues: Orthologues: chimpanzee NTSR2 (94% identical), macaque NTSR2 (87% identical), mouse Ntsr2 (79% identical), rat Ntsr2 (79% identical), pig NTSR2 (76% identical), dog NTSR2 (73% identical), rabbit NTSR2 (73% identical), tropical clawed frog ntsr2 (44% identical). Paralogues in human: NTSR1 (36% identical), NMUR1 (26% identical), MLNR (25% identical), GPR39 (23% identical), GHSR (23% identical), NMUR2 (21% identical), TRHR (19% identical), BRS3 (18% identical), EDNRB (18% identical), EDNRA (18% identical), GRPR (17% identical), NMBR (17% identical), and 3 more.
Diseases named in the same sentence as NTSR2 in open-access papers:
NTSR2 is named in the same sentence as 25 diseases in open-access papers, as found by Europe PMC text mining. Sharing a sentence is not in itself a finding about the gene and the disease. The quoted sentences say what the papers report.
prostate carcinoma (6 papers, 2015 to 2024). A carcinoma that arises from epithelial cells of the prostate gland. "In contrast, the low-affinity NTSR2, which shares 60% homology with NTSR1, demonstrates a more localized distribution; the expression of NTSR2 has been recently reported in prostate cancers and B cell lymphomas." (PMID 26298774, 2015). "NTS was acutely induced by androgen deprivation in animal models of prostate cancer (PCa) and activated downstream signaling leading to NED through activation of neurotensin receptor 1 (NTSR1) and neurotensin receptor 3 (NTSR3), but not neurotensin receptor 2 (NTSR2)." (PMID 30770901, 2019).
Anxiety (5 papers, 2013 to 2024). Intense feelings of nervousness, tension, or panic often arise in response to interpersonal stresses. "NT, NTSR1, and NTSR2, are present in several brain regions that are implicated in anxiety and depression, such as the prefrontal cortex, amygdala, and hippocampus." (PMID 37534788, 2024). "NTSR2 mRNA and NTSR2 binding was reported to be down regulated in transgenic mice over expressing corticotrophin releasing factor, which is linked to anxiety, stress and depression." (PMID 24391664, 2013). "NTSR2 mRNA and NTSR2 binding were reported to be down-regulated in transgenic mice expressing anxiety, stress, and depression." (PMID 37275985, 2023). "We observe significant enrichment of NTSR2, GPR88 and Gabrg1 in chloroquine-activated neurons, and relatively lower expression of OPRM1, PENK and Chrm1, suggesting that these genes could be critical candidates in regulating pruritis and its associated anxiety." (PMID 34032210, 2021). "Stress responses and anxiety involve mainly NTSR1, but also NTSR2 and NTSR3." (PMID 37534788, 2024).
B-cell chronic lymphocytic leukemia (3 papers, 2018 to 2024). "NTSR2 expression has been reported in prostate cancer, glioma and chronic lymphocytic leukaemia (CLL)." (PMID 32336282, 2020). "NTSR2 and NTSR3 were also overexpressed in chronic lymphocytic leukaemia (CLL) B cells." (PMID 32336282, 2020).
alcohol dependence (2 papers, 2016 to 2020). Physical and psychological dependence on alcohol. "The neurotensin receptor 2 gene (Ntsr2) has two SS in intron 2 and has been implicated in alcohol dependence with conduct disorder and suicide attempts in humans." (PMID 27490364, 2016). "Although the direct biological function of NTSR2 in alcohol dependence is still unclear, previous studies reported the potential function of the neurotensin-containing pathway in linking the hippocampal and mesolimbic dopamine systems in response to drug addiction." (PMID 27490364, 2016).
colorectal cancer (2 papers, 2020 to 2021). A primary or metastatic malignant neoplasm that affects the colon or rectum. "In vitro study published in 2015, focusing on human colorectal cancer cell lines corresponding to different colorectal cancer stages, showed variable NTS and NTSR1 expressions, no expression of NTSR2 and constant NTSR3 expression." (PMID 33268796, 2020).
depression (2 papers, 2023 to 2024). "NTSR1 and NTSR3 are primarily implicated in depression, while NTSR2 and secondarily NTSR1 in PTSD." (PMID 37534788, 2024).
glioma (2 papers, 2017 to 2019). A benign or malignant brain and spinal cord tumor that arises from glial cells (astrocytes, oligodendrocytes, ependymal cells). "Activated NTSR2 is the key regulatory component that promotes the phosphorylation of extracellular signal-regulated kinase 1/2 (ERK1/2) in glioma cells." (PMID 28458684, 2017).
pancreatic cancer (2 papers, 2021 to 2025). "We clearly demonstrated that highly malignant pancreatic cancer cells express NTSR1, not NTSR2 and SORT1, as a receptor for NTS." (PMID 33034134, 2021).
itch (1 paper, 2021). "We observed considerable overlap between NTSR2+ve (75.31% cells), GPR88+ve (69.35%) and Gabrg1+ve (62.32% cells) cells with itch-activated Fos+ve cells in the CeA." (PMID 34032210, 2021).
leukemia (1 paper, 2018). A malignant (clonal) hematologic disorder, involving hematopoietic stem cells and characterized by the presence of primitive or atypical myeloid or lymphoid cells in the bone marrow and the blood. "Because BDNF stimulation promoted formation of the NTSR2–TrkB complex in leukemia cells, we analyzed both BDNF expression in B-CLL and circulating BDNF in plasma derived from B-CLL patients or HDs." (PMID 29059151, 2018).
cancer (8 papers, 2017 to 2024). A tumor composed of atypical neoplastic, often pleomorphic cells that invade other tissues. "The GPCR family members include the neurotensin receptors, of which there are two subtypes, NTSR1 and NTSR2, which are associated with carcinogenesis, cancer progression, and prognosis." (PMID 31974445, 2020). "Neurotensin and its receptors including NTSR2 play an important role in oncogenic progression of cancer malignancies." (PMID 28458684, 2017). "Intriguingly, genes enriched in the blue NTSR2 module, such as zinc ribbon domain-containing proteins, EF-hand and calcium ion binding proteins, and P-glycoproteins, are also associated with MDR in cancer cells." (PMID 33747015, 2021). "NTSR1, NTSR2, GHSR, MLNR, and NMUR1 promoter hypermethylation presented discriminative ROC curve profiles, which clearly differentiate cancer tissues from normal tissues [Area Under Curve (AUC) = 0.6220, 0.5736, 0.8103, 0.6049, and 0.5631, respectively]." (PMID 31974445, 2020). "One of the most studied neuropeptides involved in cancer progression is neurotensin (NTS), the three known receptors of which (two G-protein coupled receptors, NTSR1 and NTSR2, and a type I receptor, NTSR3) are expressed in numerous cancers and particularly in digestive cancers." (PMID 36233189, 2022).
infection (2 papers, 2016 to 2021). The state of being infected such as from the introduction of a foreign agent such as serum, vaccine, antigenic substance or organism. "Genevestigator analysis revealed that HUB genes associated with both the NTSR2 and NTSR3 phenotypes corresponded with transcripts linked to responses to biotic (infection with Fusarium graminearum or Puccinia striiformis) and abiotic (cold and osmotic) stresses in cereals." (PMID 33747015, 2021).
tumor (2 papers, 2015 to 2021). "Further work is required to elucidate the detailed mechanisms for epigenetic silencing of NTSR1 and NTSR2 in diverse tumor types." (PMID 26298774, 2015).
NTSR2 also shares sentences with these, for which no sentence is quoted: lymphoma (2 papers); B cell lymphomas (1); breast carcinoma (1); conduct disorder (1); metabolic disorders (1); migraine (1); myeloma (1); neuroblastoma (1); neuroendocrine tumors (1); Obesity (1); renal cell carcinoma (1); Sezary syndrome (1).